POU2F1 (POU class 2 homeobox 1)
Diseases named in the same sentence as POU2F1 in open-access papers (continued):
Sharing a sentence is not in itself a finding about the gene and the disease.
tumor (continued). "The 18F-FDG PET/CT of tumor-bearing mice also exhibited that the maximum standard uptake values (SUV max) in the mice bearing POU2F1 silencing tumors were significantly less than that in the mice with control tumors (p < 0.001)." (PMID 34997215, 2022). "Increasing studies have revealed that POU2F1, as a multifunctional transcription factor, promoted tumorigenesis and progression through modulation of tumor-specific gene expression." (PMID 34257651, 2021). "Here, we found that POU2F1 was highly expressed in GC patients and promoted cell viability, invasion, migration in vitro, as well as tumor growth in vivo." (PMID 34257651, 2021). "Function analysis revealed that POU2F1 promoted GC cell viability, migration and invasion, and tumor growth through upregulation of TTC3-AS1." (PMID 34257651, 2021). "In order to investigate the tumor-growth function of POU2F1/TTC3-AS1 in GC, the transfected SGC7901 cells were subcutaneously injected into the left flanks of male athymic BALB/c nude mice, and GC tumorigenesis was evaluated." (PMID 34257651, 2021). "In conclusion, the study illustrated that POU2F1 promoted GC cell viability, invasion, and migration as well as tumor growth in vivo through direct transcription activation of TTC3-AS1." (PMID 34257651, 2021). "Owing to the epigenetic effect, the target gene SMC2 promotes tumor apoptosis and inhibits the cell cycle; the target gene POU2F1 inhibits cell proliferation; and the target gene GDNF inhibits cell migration and proliferation." (PMID 32211020, 2020). "The Univariate analyses revealed that POU2F1 expression level, tumor size, PVTT, metastasis and clinical stage were significant predictors of OS." (PMID 28489585, 2017). "Our findings indicated that up-regulation of POU2F1 positively correlated with tumor size (≥ 5 or < 5 cm) (P = 0.007), histological grade (P = 0.019), HCC metastasis (P = 0.044) and the clinical stage (P = 0.0004)." (PMID 28489585, 2017). "The reduction of miR-9-5p, miR-144, miR-145 and miR-229 leads to tumor progression through the miR-9-5p/POU2F1, miR-144/c-Met, miR-145/ZEB2 and miR-229/VEGFA signaling pathway." (PMID 28548946, 2017). "It has been shown that POU2F1 acts not only as an oncogene but also as a tumor suppressor gene in different cancers." (PMID 28489585, 2017). "In patient tumor tissue samples (n=8) the level of POU2F1 was higher by 5.3-fold compared to matched control samples (P<0.05) by Q-PCR." (PMID 25301728, 2014). "At 8.3-weeks post-HDTVi, there was an increase in gross tumor burden and significant increase in liver weight, LW/BW, and spleen weight in β-M-POU2F1 + αCD3 versus β-M-POU2F1 + IgG animals, suggesting an immune-dependent role for POU2F1-mediated tumor regression in CTNNB1-mutated HCC." (PMID 40442146, 2025). "Interestingly, at 8.3-weeks post-HDTVi, there was a significant increase in tumor burden in β-M-POU2F1 + βCD3 versus β-M-POU2F1 + IgG animals, suggesting an immune-dependent role for POU2F1-mediated tumor regression in CTNNB1-mutated HCC." (PMID 39711542, 2024). "POU2F1 is overexpressed in many cancers and tumor cell lines." (PMID 35538289, 2022). "The tumor-promoting properties of POU2F1 OE was partially rescued by LINC01564 knockdown." (PMID 35562740, 2022). "Accumulated evidence has indicated that POU2F1 functions as an oncogene in tumor progression." (PMID 34257651, 2021). "Rescue experiments revealed that TTC3-AS1 knockdown could reverse the protumor effects of POU2F1 in GC cells as well as tumor growth in vivo." (PMID 34257651, 2021). "POU2F1 is usually overexpressed in NHL, which may lead to higher susceptibility to therapies as irinotecan, paclitaxel, and mutations on POU2F1 may lead to tumor resistance against chemotherapies." (PMID 33591648, 2021). "In summary, POU2F1/TTC3-AS1 axis promoted tumor growth in GC." (PMID 34257651, 2021). "POU2F1/TTC3-AS1 was upregulated in GC tumor tissues and predicted poor prognosis in GC patients." (PMID 34257651, 2021).
tumor (continued). "In addition to a high POU2F1 expression level, a tumor ≥ 5 cm, clinical stage III-IV, the presence of PVTT and HCC metastasis were also associated with shorter OS and higher death rates." (PMID 28489585, 2017). "In addition, we investigate whether LINC01564 affects the GC tumor progression through its interaction with transcription factor POU2F1." (PMID 35562740, 2022). "POU2F1, which is also known as OCT1, promotes tumor growth and metastasis by activating downstream signaling pathways in liver cancer, colon cancer, ovarian cancer, and gastric cancer." (PMID 35313857, 2022). "In this study, we also identified that POU2F1 and its potential target TTC3-AS1 were significantly upregulated in GC tumor tissues, compared with normal tissues." (PMID 34257651, 2021). "The results showed that GC tumor growth was significantly enhanced by POU2F1-OE, compared with the NC group, while cotransfection of TTC3-AS1-KD inhibited GC tumor growth." (PMID 34257651, 2021). "In GE2-HCC, top potential transcriptional activators included transcription factors with reported tumour-promoting activity in HCC and/or other cancer types, e.g., NKX6-1, POU2F1/2, cJUN, E2F1, HSF2, SRF, TFCP2 and NFY." (PMID 33541355, 2021). "POU2F1 mRNA and protein levels were elevated in all HCC compared with matched adjacent non-tumor hepatic tissues." (PMID 28489585, 2017). "The high POU2F1 protein expression level positively correlated with large tumor size, high histological grade, tumor metastasis and advanced clinical stage, and HCC patients with high POU2F1 levels exhibited poor prognoses." (PMID 28489585, 2017). "We found that POU2F1 is highly expressed in HNSCC cell lines compared to NOKs, and in patient tumor samples compared to tissue-matched control samples." (PMID 25301728, 2014). "We identified through unbiased bulk RNA-seq, scRNA-seq, and spatial transcriptomic approaches tumor-cell-intrinsic roles of β-catenin-mediated IRF2 and POU2F1 repression driving an immune-excluded TIME and inert type I/II IFN responses in β-catenin-mutated HCC with in vivo validation." (PMID 40442146, 2025). "We identified through unbiased scRNA-seq and spatial transcriptomic approaches a novel tumor-cell intrinsic role of β-catenin-mediated IRF2 and POU2F1 repression driving an immune excluded TIME and inert type I/II interferon responses in β-catenin-mutated HCC with in vivo validation." (PMID 39711542, 2024). "In addition, T3 had 120 mutations not found in the other tumours, including, for example, variants in ILF2 and IL7R, which regulate immune function, and in EP400 and POU2F1, which contribute to DNA repair mechanisms." (PMID 34299215, 2021). "However, currently, there is no study exploring whether POU2F1 is involved in lncRNA expression in the tumor." (PMID 34257651, 2021).
cancer (24 papers, 2009 to 2025). A tumor composed of atypical neoplastic, often pleomorphic cells that invade other tissues. "However, silencing of LINC01564 significantly reversed the oncogenic roles of POU2F1 in GC in vitro and in vivo, which supported that the cancer-promoting effects of POU2F1 was associated with LINC01564." (PMID 35562740, 2022). "In addition, Spp1/Opn, as a POU2F1 target gene, encodes osteopontin reported to be highly expressed in several cancers involving GC." (PMID 34257651, 2021). "For example, OCT4 is important for stemness of cancer stem cells and POU2F1 expression is up-regulated in head and neck squamous carcinoma." (PMID 34997215, 2022). "POU2F1 (Oct-1) is a transcription factor, the overexpression of which is found in many human malignant tumors; a significant increase in its level in cells determines the malignant potential of the tumor." (PMID 33689071, 2021). "POU2F1 (Oct-1) is a pro-oncogenic factor and has prognostic value in the development and treatment of a wide range of malignant tumors." (PMID 33689071, 2021). "POU2F1 has already emerged as a prognostic marker and a potential therapeutic target in several types of cancer including HCC." (PMID 33541355, 2021). "Recent studies into POU2F1 have focused on its impacts on cancers and tumors, especially hepatocellular carcinoma." (PMID 32443864, 2020). "The wide involvement of POU2F1 in various kinds of cancer and in the immune response to cancers suggests its general expression in different organs, which was also found in this study." (PMID 32443864, 2020). "Among the top 10 DRGs identified for Korean (GSE24375), six genes are GC related (ESRRG, LIMS1, GATA3, GATA6, SOX9, POU2F1) and the other four are cancer related (IRF2, RGS3, MRPL36, FOSB)." (PMID 29745833, 2018). "The POU2F1 has recently been suggested to play a crucial role in the tumourigenesis of several types of human cancer." (PMID 28489585, 2017). "It was also found that miR-449a expression was greatly downregulated in cancer tissues of liver compared with that of normal ones and negatively associated with CAPN6 and POU2F1." (PMID 26375440, 2016). "Further research demonstrated that miR-449a inhibited cancer cell proliferation and induced apoptosis via suppressing both POU2F1 and CAPN6." (PMID 26375440, 2016). "Functionally, POU2F1 can regulate carcinogenesis and cancer progression." (PMID 34997215, 2022). "Our study in vitro confirmed that the cancer-promoting effects of POU2F1 is dependant on LINC01564." (PMID 35562740, 2022). "LINC01564 knockdown abolished the cancer promoting effects conferred by overexpressed POU2F1." (PMID 35562740, 2022). "The fact that POU2F1 is important for the cell response to genotoxic and oxidative stress, but is not critical under standard conditions, makes its inhibition an attractive anti-cancer therapeutic approach." (PMID 33541355, 2021). "NFTA5 and POU2F1 were also demonstrated to participate in cancer regulation." (PMID 34513699, 2021). "Intersecting the sets of pan-cancer compensated and toxic genes yields nine high-confidence ARGOS genes, six of which are also frequently amplified: RBM12, RBM14, SNRPA, ZBTB14, POU2F1, and CDKN1A." (PMID 39870664, 2025). "Some TFs in the module have been demonstrated to involve in cancer procession, such as CHD1, NFAT5, and POU2F1." (PMID 34513699, 2021). "As such, special attention in future analyses should be paid to the linking genes PRKCA, PTPN14, POU2F1, and TGFBR1, because of their possible roles in cancer initiation." (PMID 30045691, 2018). "PO-MSCs showed the representative participation of POU2F1 (15.7%, p = 0.03) and TFAP4 (12.5%, p = 0.02) as main transcriptional regulators at upregulated genes, which are related to cancer stem cells, cell cycle, and histone regulation." (PMID 28194153, 2017). "POU2F1 induced the transcription of Twist1, Snai1, Snai2 and ZEB1 genes which induce cancer cell EMT." (PMID 28489585, 2017).
cancer (continued). "Collectively, these findings showed that POU2F1 induced the transcription of Twist1, Snai1, Snai2 and ZEB1 genes which induce cancer cell EMT." (PMID 28489585, 2017). "The role of ELK1 in cancer cell aggressiveness was also validated by another study focusing on Octamer transcription factor 1 (OCT1; also known as POU domain, class 2, transcription factor 1, POU2F1)." (PMID 40862737, 2025). "Additionally, the gene targets of these miRNAs included several cancer driver genes including ZNF704 (targeted by ten miRNAs), MMP16 (targeted by eight miRNAs), and KCNN3, POU2F1, ADARB1, MPZL1, RUNX1T1, UBE2W, and DYRK1A genes (targeted by seven miRNAs)." (PMID 37685851, 2023). "In the case of the POU2F1 gene in humans and primates, this transformation led to the emergence of the new POU2F1Z isoform, which protects cells from the damaging effects of cellular stress but creates difficulties for the treatment of malignant neoplasms." (PMID 35538289, 2022). "It has been disclosed that POU2F1 promoted EMT by targeting TWIST1 and SLUG, which are part of a group of TFs inducing EMT in cancer cells, therefore facilitating the invasion and metastasis of cancer cells." (PMID 34257651, 2021). "The detailed mechanisms of actions for MYB family in cancer development involving other transcription factor partners, such as SALL2, XBP1, and POU2F1, are still not clear." (PMID 24639887, 2014).
infection (3 papers, 2013 to 2022). The state of being infected such as from the introduction of a foreign agent such as serum, vaccine, antigenic substance or organism. "POU2F1 is a required transcription factor for T-cell response to infection and the development of CD4+ memory T-cells." (PMID 36225796, 2022). "In CD4+ T cells, the transcription factor Oct1/Pou2f1 is a dispensable transcription factor for T cell development and response to primary infection, but promotes expression of target genes, including Il2 and Ifng, under conditions of antigen reencounter." (PMID 31266507, 2019). "Oct1/Pou2f1 is a POU-domain transcription factor that in mice is dispensable for T cell development and response to primary infection but is important for the formation of CD4+ central memory cells." (PMID 31266507, 2019).
POU2F1 also shares sentences with these, for which no sentence is quoted: Burkitt lymphoma (2 papers); esophageal cancer (2); liposarcoma (2); lymphoma (2); Type 2 Diabetes (2); asthma (1); brain tumors (1); cerebral tumor (1); colorectal tumors (1); diabetic retinopathy (1); gastric tumor (1); head and neck squamous cell carcinoma (1); Hyperglycemia (1); liver diseases (1); melanoma (1); metastatic tumor (1); neuroblastoma (1); ovarian carcinoma (1); systemic lupus erythematosus (1); triple-negative breast carcinoma (1); viral infection (1).